SGK3 (serum/glucocorticoid regulated kinase family member 3)
Description:
Serine/threonine-protein kinase which is involved in the regulation of a wide variety of ion channels, membrane transporters, cell growth, proliferation, survival and migration. Up-regulates Na(+) channels: SCNN1A/ENAC and SCN5A, K(+) channels: KCNA3/KV1.3, KCNE1, KCNQ1 and KCNH2/HERG, epithelial Ca(2+) channels: TRPV5 and TRPV6, chloride channel: BSND, creatine transporter: SLC6A8, Na(+)/dicarboxylate cotransporter: SLC13A2/NADC1, Na(+)-dependent phosphate cotransporter: SLC34A2/NAPI-2B, amino acid transporters: SLC1A5/ASCT2 and SLC6A19, glutamate transporters: SLC1A3/EAAT1, SLC1A6/EAAT4 and SLC1A7/EAAT5, glutamate receptors: GRIA1/GLUR1 and GRIK2/GLUR6, Na(+)/H(+) exchanger: SLC9A3/NHE3, and the Na(+)/K(+) ATPase. Plays a role in the regulation of renal tubular phosphate transport and bone density. Phosphorylates NEDD4L and GSK3B. Positively regulates ER transcription activity through phosphorylation of FLII. Negatively regulates the function of ITCH/AIP4 via its phosphorylation and thereby prevents CXCR4 from being efficiently sorted to lysosomes.
Synonyms: CISK; SGKL; SGK2
Tractability: Small molecule: a high-quality ligand is known; it belongs to a druggable protein family. PROTAC: it is named in the literature on targeted protein degradation; ubiquitination databases record sites on it; its protein half-life has been measured; a small molecule that binds it is known.
Target class: AGC protein kinase group; AGC protein kinase SGK family; Enzyme; Kinase; Protein Kinase
Chemical probes: PROTAC SGK3 degrader-1 (high quality)
Gene: Protein-coding gene on chromosome 8 (66,712,484 to 66,862,022, forward strand). Ensembl gene ENSG00000104205.
Subcellular location: Cytoplasmic vesicle; Early endosome; Recycling endosome
Subcellular location (Human Protein Atlas): Vesicles; Nucleoplasm
Pathways (Reactome):
Transport of small molecules: Stimuli-sensing channels
Gene Ontology:
Molecular function: protein binding; protein serine/threonine kinase activity; calcium channel regulator activity; chloride channel regulator activity; potassium channel regulator activity; protein kinase activity; sodium channel regulator activity; ATP binding; phosphatidylinositol binding; protein serine kinase activity
Biological process: intracellular signal transduction
Cellular component: cytosol; cytoplasm; cytoplasmic vesicle; early endosome; recycling endosome
Genetic constraint (gnomAD): Loss-of-function variants: 44 observed, 65.2 expected, observed/expected ratio (o/e) 0.67, 90% interval 0.53 to 0.87. The upper end of that interval is the gene's LOEUF score, 0.87, which puts it in group 3 of 6, group 1 being the genes least tolerant of losing a copy. Missense variants: 479 observed, 589.95 expected, observed/expected ratio (o/e) 0.81, 90% interval 0.75 to 0.88. Synonymous variants: 181 observed, 192.04 expected, observed/expected ratio (o/e) 0.94, 90% interval 0.83 to 1.07.
Homologues: Orthologues: chimpanzee SGK3 (99% identical), macaque SGK3 (99% identical), dog SGK3 (98% identical), pig SGK3 (98% identical), rabbit SGK3 (98% identical), guinea pig SGK3 (97% identical), mouse Sgk3 (97% identical), rat Sgk3 (97% identical), zebrafish sgk3 (77% identical), tropical clawed frog sgk3 (77% identical), Caenorhabditis elegans sgk-1 (43% identical). Paralogues in human: SGK1 (60% identical), SGK2 (50% identical), MAST2 (33% identical), MAST3 (32% identical), MAST1 (32% identical), MAST4 (32% identical), LATS1 (26% identical), LATS2 (25% identical), DMPK (24% identical), STK32C (23% identical), MASTL (22% identical), STK32B (21% identical), and 1 more.
Diseases named in the same sentence as SGK3 in open-access papers:
SGK3 is named in the same sentence as 58 diseases in open-access papers, as found by Europe PMC text mining. Sharing a sentence is not in itself a finding about the gene and the disease. The quoted sentences say what the papers report.
breast cancer (36 papers, 2014 to 2025). A primary or metastatic malignant neoplasm involving the breast. "Studies have found that SGK3 was transcriptionally activated by estrogen receptor ESR1 and high SGK3 expression was associated with poor prognosis of HR+ breast cancer patients." (PMID 40303291, 2025). "SGK3 is involved in the resistance to class 1 PI3K or Akt inhibitors in breast cancer as SGK3 can substitute for the loss of Akt activity and restore proliferation." (PMID 32668203, 2020). "Evidence includes a study demonstrating that PDK1-mediated SGK3 activation was critical for anchorage-independent growth in a subset of PIK3CA (the gene encoding for p110α) mutant breast cancer cell lines with minimal Akt activation." (PMID 31088502, 2019). "In breast cancer cells, increased SGK3 phosphorylation was associated with increased INPP4B expression, as well as PIK3CA and PTEN mutations." (PMID 28082369, 2017). "SGK3 has been shown in additional studies to be linked with breast cancer and is induced by estrogen in breast cancer cells and is associated with ER expression." (PMID 25051360, 2014). "Interestingly, SGK1 and SGK3 have also been linked to PI3K/AKT-targeted therapy resistance in breast cancer." (PMID 32630372, 2020). "Recent studies have indicated an association between high INPP4B expression and SGK3 phosphorylation levels in PIK3CA-mutant breast cancers and melanoma, in which INPP4B-mediated activation of SGK3 enhances cell proliferation and promotes anchorage-independent cell growth." (PMID 29343273, 2018). "Taken together, enhanced stemness property and activated ESR1/SGK3/GSK3β/β-catenin pathway was discovered in the alpelisib-resistant breast cancer cells." (PMID 40303291, 2025). "This set of experiments suggested that SGK3 was able to promote the stemness of breast cancer cells and resistance to BYL719." (PMID 40303291, 2025). "Both overexpression and knockdown experiments demonstrated that SGK3 was involved in the regulation of alpelisib resistance in breast cancer." (PMID 40303291, 2025). "In our study, both VPS34-IN1 and SGK3-PROTAC1 exhibited cytotoxic effects on the alpelisib-resistant breast cancer cells." (PMID 40303291, 2025). "Consistent with this, we observe that SGK3 depletion elevates NOTCH1 levels in breast cancer cells, including the triple negative CAL-51 line, as it does in MCF10A cells." (PMID 39663000, 2025). "In Kaplan-Meier analysis, high SGK3 expression correlated with shorter disease-free survival of luminal breast cancer patients when compared with cases with low SGK3 expression." (PMID 40303291, 2025). "INPP4B was described as an oncogene by SGK3 activation in melanoma, breast cancer, and colon cancer." (PMID 35075772, 2022). "As serum glucocorticoid-regulated kinase 3 (SGK3) is a transcriptional target for ERα and promotes ER+ breast cancer cell survival, we irradiated MCF7 and T47D cells with different doses of X-rays and found that SGK3 expression declined." (PMID 34716300, 2021). "It has been shown that SGK3 plays a role as a carcinogen in breast cancer, ovarian cancer, and hepatocellular carcinoma, and it participates in controlling cell survival, differentiation, and material transport." (PMID 34046405, 2021). "For example, in breast cancer SGK3 is amplified and its kinase activity is dependent on oncogenic PI3K and INPP4B23." (PMID 34035258, 2021). "PI3K or Akt inhibitors activate and increase SGK3 expression in patients with ER+ breast cancer (BC) receiving long-term treatment." (PMID 34277564, 2021). "Gasser and colleagues have also shown that INPP4B over-expression leads to enhanced SGK3 activation in ZR-75-1 breast cancer cells, triggering a switch from AKT- to SGK-dependent signaling downstream of PDK1." (PMID 32630372, 2020). "The results corroborate a previous study showing that SGK3 is required for the growth of PIK3CA E545K mutant breast cancer cells." (PMID 30975125, 2019).
breast cancer (continued). "SGK3 has been reported to be a critical effector of oncogenic PIK3CA mutant breast cancer cells in which Akt is dispensable." (PMID 29940988, 2018). "A previous study showed that PIK3CA-mediated breast cancer cell growth and survival are dependent on the SGK3, and Akt is dispensable." (PMID 29940988, 2018). "Previous studies also reported that SGK3 is an ERα transcriptional target and promotes estrogen-mediated cell survival of ERα-positive breast cancer cells." (PMID 26795955, 2016). "A recent study suggested that SGK3 promotes breast cancer through an Akt-independent mechanism and promotes cell proliferation and survival in hepatocellular carcinoma." (PMID 27602769, 2016). "Studies suggest that SGK3 has strong oncogenic potential and is amplified and hyperactivated in breast cancer and hepatocellular carcinoma." (PMID 27602769, 2016). "We demonstrate that sustained suppression of Class I PI3K or Akt activity over several days triggers the selective upregulation of SGK3 mRNA and protein as well as its catalytic activity in a variety of breast cancer cell lines." (PMID 27481935, 2016). "By analogue, INPP4B is known to activate SGK3 and drive tumourigenesis in a subset of breast cancers with low Akt." (PMID 26573229, 2015). "Nevertheless, INPP4B-dependent activation of SGK3 drives tumourigenesis in a subset of breast cancers with low Akt." (PMID 26573229, 2015). "Similarly, SGK3 expression was also markedly higher in luminal breast cancer patients who were resistant to a PI3K/mTOR inhibitor NVP-BEZ235 as estimated by the DeepDR analysis." (PMID 40303291, 2025). "Taken together, these results suggested SGK3 could be a promising target for alpelisib-resistant breast cancer." (PMID 40303291, 2025). "Interestingly, resistance to mTOR inhibition in breast cancer cells is mediated by hVPS34 and SGK3, defining an AKT independent mTOR activation pathway." (PMID 39663000, 2025). "Additionally, we observed that SGK3 promoted tumor cell stemness by activating GSK3β/β-catenin signaling pathway, leading to the resistance to alpelisib in breast cancer." (PMID 40303291, 2025). "Collectively, these findings suggest that SGK3 could be a novel therapeutic target for breast cancer patients who developed resistance to alpelisib." (PMID 40303291, 2025). "It was also reported that inhibition of SGK3, a downstream kinase of ERα in breast cancer, could drastically suppress aromatase inhibitors (AI)-resistant tumor cell survival via inducing intense ER stress." (PMID 35784473, 2022). "Similarly, SGK3 was also found to be a key mediator of PDPK1‐dependent melanomagenesis and a driver for tumour formation in breast cancer cells in both PIK3CA wild‐type and mutated cells in an AKT‐independent manner." (PMID 32926495, 2020). "Sun found that SGK3 expression could promote the proliferation, survival, invasion and migration of breast cancer cells." (PMID 30108027, 2019). "In addition, INPP4B has been known to activate SGK3 and drive tumorigenesis in a subset of breast cancers with low levels of AKT." (PMID 29343273, 2018). "Indeed, several reports have described the contribution of SGK1 and/or SGK3 to cancer progression, and a recent report identified a subset of breast-cancer cell lines that are intrinsically resistant to Akt inhibition due to constitutive upregulation of SGK1." (PMID 24558442, 2014). "In breast cancer cells with PIK3CA mutation, PI3K inhibition resulted in enhanced estrogen receptor function 19, 20, which might subsequently upregulate the expression of SGK3." (PMID 40303291, 2025). "Similarly, PROTACs using biochemical inhibitors were designed to tag SGK3 kinase with VHL ubiquitin ligases to facilitate selective and efficient degradation of SGK3 in breast cancers compared to conventional inhibitors because of their sub-stoichiometric catalytic mode of action." (PMID 34552611, 2021).
breast cancer (continued). "Therefore, upregulation of SGK3, which we observed in our models of Akt‐sensitive breast cancer cell lines, could serve as a strategy to circumvent inhibition of Class I PI3K as well as Akt isoforms and provide adaptive resistance response." (PMID 27481935, 2016). "The therapeutic potential of SGK3 inhibition has been particularly promising in oncology, where it overcomes drug resistance in HER2+ breast cancer and counteracts rapamycin resistance via mTORC1 reactivation." (PMID 40767604, 2025). "Concordant with functional experiments, SGK3 overexpression led to elevated expression of stem cell marker CD44 and c-Myc in breast cancer cells." (PMID 40303291, 2025). "In our model, SGK3 and ESR1 were markedly upregulated in alpelisib-resistant breast cancer cell lines." (PMID 40303291, 2025). "In our study, SGK3 was demonstrated to be responsible for the resistance to BYL719 and enhanced breast cancer stemness by increasing the phosphorylation levels of GSK3β and β-catenin." (PMID 40303291, 2025). "The prolonged treatment of breast cancer cells with class I PI3K or AKT inhibitors leads to the increased expression and activation of a kinase termed SGK3 which is related to AKT." (PMID 36765741, 2023). "For example, the treatment of breast cancer cells with PI3K or AKT inhibitors results in increased expression and the activation of SGK3, which depends on hVps34 for activation by PDK1 and mTORC242." (PMID 33960177, 2021). "Mounting evidence indicates that SGK3 is involved in the development and progression of several cancers, including HCC, breast cancer, prostate cancer, and melanoma." (PMID 30975125, 2019). "A recent study reported that prolonged treatment of breast cancer cells with class I PI3K or Akt inhibitors leads to increased expression and activation of SGK3." (PMID 29940988, 2018). "In another study, prolonged treatment of breast cancer cell lines with Class 1 PI3K or Akt inhibitors induced resistance, by increasing the expression and activation of SGK3." (PMID 29150437, 2018). "Prolonged treatment of breast cancer cells with PI3K or Akt inhibitors leads to increased expression and activation of a kinase termed SGK3 that is related to Akt." (PMID 27481935, 2016). "We characterise 14h, a compound that inhibits both SGK3 activity and activation in vivo, and show that a combination of Akt and SGK inhibitors induced marked regression of BT‐474 breast cancer cell‐derived tumours in a xenograft model." (PMID 27481935, 2016). "Moreover, a synergistic interaction between SGK3-PROTAC1 and BYL719 was demonstrated by CCK-8 assay, suggesting that SGK3 inhibitors should be promising treatment strategies for breast cancer patients who had developed resistance to alpelisib." (PMID 40303291, 2025). "Serum/glucocorticoid regulated kinase family member 3 (SGK3), a member of Aggrecan (AGC) protein kinase family member, acts as an oncogene in human cancers such as osteosarcoma (OS), hepatocellular carcinoma (HCC) and breast cancer." (PMID 34740363, 2021). "In a subset of breast cancer cell lines, hyperactivation of PI3K pathways was reported to be independent from Akt activation and it was shown that tumourigenicity of the cells, as assessed by anchorage-independent growth, was dependent on PDK1 and SGK3." (PMID 31088502, 2019). "In addition, silencing of SGK3 has been proven to inhibit the growth of prostate cancer, HCC, melanoma, and breast cancer cell lines." (PMID 30975125, 2019). "The recent emergence of serum and glucocorticoid-regulated kinase (SGK3) as an oncogenic effector in PIK3CA-mutant breast cancer cells independent of AKT has led to the examination of INPP4B as a mediator of PI3K/SGK3 signalling." (PMID 28082369, 2017). "To test whether PTPN23, HCN2, or SGK3 affect Notch levels in breast cancer cells, we first evaluated by Western blot the levels of NOTCH1-3 in a panel of five breast cancer lines of different origin." (PMID 39663000, 2025).
breast cancer (continued). "For instance, cophosphorylation of Serum/glucocorticoid-regulated kinase 3 (SGK3) with GSK-3β enhances the binding of FBXW7 to metastasis suppressor N-Myc downstream regulated gene 1 (NDRG1) and promotes NDRG1's ubiquitination, increasing breast cancer invasion and metastasis." (PMID 37658431, 2023). "Also, the PIK3CA E545K mutant form promotes growth of breast cancer cells by activation of SGK3, but not AKT." (PMID 30975125, 2019). "shRNA knockdown of INPP4B in MCF-7 and ZR-75-1 breast cancer cells, which express high levels of SGK3, reduced anchorage-independent cell growth, cell migration, 3D colony formation and mouse xenograft tumour growth as well as inhibiting IGF-1-stimulated SGK3 phosphorylation." (PMID 28082369, 2017). "Studies indicated a correlation between high INPP4B expression and SGK3 phosphorylation levels in breast cancer and melanoma cells, in which INPP4B overexpression triggered phosphorylation and activation of SGK3, not AKT." (PMID 36993823, 2023). "Thus, it is not surprising that SGK3 has been found to be upregulated in a variety of human tumors, including HCC, breast cancer, and colon cancer." (PMID 30975125, 2019).
hepatocellular carcinoma (11 papers, 2015 to 2022). A malignant tumor that arises from hepatocytes. "miR-144-3p was significantly downregulated in hepatocellular carcinoma, glioblastoma, multiple myeloma and pancreatic cancer and inhibited proliferation, migration and tumour metastasis by targeting SGK3, FZD7, c-Met and FOSB." (PMID 31552107, 2019). "Liu found that SGK3 overexpression was significantly associated with a poor prognosis and more common than AKT overexpression in hepatocellular carcinoma." (PMID 30108027, 2019). "To explore the relevance between SGK3 and liver CSCs, we detected expression levels of SGK3 mRNA in CSC-enriched hepatoma spheroids compared with monolayer-attached cells." (PMID 29940988, 2018). "Future in vivo experiments will be performed to study the role of SGK3 in hepatocellular cancer stem cells to characterize the pathogenesis of HCC." (PMID 27602769, 2016). "The amplification and overexpression of SGK3 is more common than AKT in hepatocellular carcinoma, suggesting it may have a greater functional significance in the biology of this type of cancer." (PMID 33960177, 2021). "Moreover, the study also found that overexpression of SGK3 in hepatocellular carcinoma cells significantly increased tumor formation and progression in nude mice compared to the use of empty vector control cells." (PMID 30108027, 2019). "A functional in vitro experiment showed that overexpression of SGK3 could promote cell growth, clonogenicity and anchorage-independent growth in hepatocellular carcinoma." (PMID 30108027, 2019). "Indeed, SGK3 contributes to the pathogenesis of various malignant tumours such as breast and ovary cancer and hepatocellular carcinoma." (PMID 26573229, 2015). "In addition, miR-144 could inhibit human hepatocellular carcinoma by regulating CCNB1, repress the mTOR-VEGF pathway by targeting SGK3 in HCC, and reverse the chemoresistance of HCC cells by suppressing Nrf2." (PMID 33526055, 2021).